CXCL8 (C-X-C motif chemokine ligand 8)
Diseases named in the same sentence as CXCL8 in open-access papers (continued):
Sharing a sentence is not in itself a finding about the gene and the disease.
pneumonitis (14 papers, 2009 to 2025). An inflammatory process affecting the lung parenchyma. "Previous studies have reported that fibrogenic cytokines including CXCL1, CXCL2, TNF-α, and CXCL8 are involved in bleomycin-induced pneumonitis." (PMID 41425704, 2025). "SsRNA stimulation of human leukocytes induced cytokines/chemokines similar to those observed in murine SARS-CoV pneumonitis including IL-1α, IL-1β, IL-6, TNF, CXCL8 (IL-8), CCL2 (MCP-1), CCL3 (MIP-1α), and CCL4 (MIP-1β)." (PMID 23236475, 2012).
aneurysm (13 papers, 2012 to 2023). Bulging or ballooning in an area of an artery secondary to arterial wall weakening. "Intragroup analysis for group 2 showed increased Pecam-1, CXCL8, resistin, osteopontin and decreased levels of leptin, pentraxin-3 in KD with aneurysms as compared to patients without CAA (non-significant)." (PMID 36096831, 2022). "Intragroup analysis for group 3 patients revealed elevated VEGF-A, CXCL8, Leptin, Pentraxin-3, resistin in patients with CAA as compared to KD without aneurysms while pecam-1, endoglin and osteopontin were comparable in both." (PMID 36096831, 2022).
chronic bronchitis (13 papers, 2009 to 2025). A type of chronic obstructive pulmonary disease characterized by chronic inflammation in the bronchial tree that results in edema, mucus production, obstruction, and reduced airflow to and from the lung alveoli. "Neutrophilia is a key feature of chronic bronchitis and a complex network of cytokines and chemokines including IL-8 (CXCL8), CXCL1/5/7 and CCL3 are known chemotactic factors for neutrophil migration to inflammatory sites through binding to CXCR1/2 and CCR1/5 receptors." (PMID 34098956, 2021). "A bronchoscopic study of 42 subjects with chronic bronchitis (with and without airflow obstruction) and 13 healthy controls found increased activity of CXCL8, myeloperoxidase, hyaluronan, and eosinophil cationic protein." (PMID 26424214, 2015).
disc degeneration (13 papers, 2011 to 2025). "Stimulation by thrombin upregulates EGFR-dependent CXCL8 expression through the Src/ERK/STAT3 signaling pathways in NP cells, which may contribute to immune cell recruitment and disc degeneration." (PMID 28819180, 2017). "Although the roles of chemokines in immune cell chemotaxis have been described in detail, the regulation of CXCL8 during disc degeneration is still not clear." (PMID 28819180, 2017).
keratitis (13 papers, 2010 to 2025). A corneal disease that is characterized by inflammation of the cornea. "The current study demonstrated that SNPs within IL1B and CXCL8 are associated with risk of developing all forms of keratitis or (at least a trend in) microbial keratitis (frank bacterial corneal infection)." (PMID 36422638, 2022). "IL-8 (CXCL8) and the mouse equivalents, MIP-2 and KC, have been shown to be key chemokines that function during keratitis to attract polymorphonuclear leucocytes to the cornea and tear film." (PMID 36422638, 2022). "Certain SNPs in IL6, CXCL8, and IL12B occurred less frequently in all keratitis cases than in controls." (PMID 36422638, 2022).
leprosy (13 papers, 2013 to 2025). Leprosy is a chronic infectious disease affecting primarily the skin and peripheral nervous system. "According to the authors, the chemokine CXCL8, which is essential in recruiting monocytes and lymphocytes into the site of infection, favors the regression of lesions in patients with leprosy." (PMID 40109344, 2025). "In the case of leprosy, we believe that the mediators CXCL8, CCL3, CXCL10, IL-9, IL-6, and IFN-γ could be considered as potential biomarkers for the future development of rapid assays that could assist in the diagnosis and prognosis of leprosy and leprosy reactions." (PMID 40109344, 2025).
Lyme disease (13 papers, 2013 to 2025). Lyme disease (named after the towns in the USA where the disease was first identified) is a bacterial infection caused by Borrelia burgdorferi. "The levels of CXCL10 and CXCL8 in the CSF have previously been shown to be elevated both in patients with neuroborreliosis and with HIV‐negative neurosyphilis." (PMID 32419252, 2020).
myocarditis (13 papers, 2017 to 2025). Myocarditis is a condition that is characterized by inflammation of the heart muscle (myocardium). "In CVB3 infection, the expression of interferon beta (IFN-β, gene IFNB1), tumor necrosis factor alpha (TNF-α, gene TNF), interleukin-1 beta (IL-1β, gene IL1B) and interleukin-8 (IL-8, gene CXCL8) are highly upregulated and correlate with myocarditis severity." (PMID 41156753, 2025).
prostate tumor (13 papers, 2013 to 2024). "CXCL8 is a pro-angiogenic chemokine; silencing of CXCL8 expression in prostate tumor cells leads to inhibition of angiogenesis and decreased prostate tumor growth." (PMID 29502208, 2018). "Our recent research has established an important contextual relationship of impaired PTEN function to the over-expression of CXCL8 in prostate tumor cells." (PMID 24970800, 2014). "High CXCL8 secreting PC3 clones were shown to produce highly vascularized prostate tumors, with a significantly higher rate of lymph node metastases than that of PC3 clones secreting low levels of CXCL8." (PMID 24276377, 2013). "The baseline and radiation-enhanced secretion of CXCL8 (and its orthologues CXCL1, CXCL2 and CXCL5) from PTEN-deficient prostate tumour epithelial cells exerts both autocrine and paracrine actions within the tumour microenvironment given the expression of CXCR1 and CXCR2 upon multiple cell types." (PMID 32743555, 2020). "Furthermore, other cytokines such as CCL2, RANKL, IL-6, CXCL8, and IL-1 are known to drive osteoclastogenesis and bone resorption: key events observed following prostate tumor metastasis to the bone." (PMID 32585812, 2020). "Therefore, pre-clinical evidence suggests that evaluating anti-CXCL8 therapeutics would be more clinically relevant in patients with confirmed PTEN+/− or PTEN−/− prostate tumors." (PMID 24276377, 2013).
Sjögren’s syndrome (13 papers, 2009 to 2025). "Pro-inflammatory cytokines IL-1β, IL-6, IL-17 and TNF-α, as well as chemokines CXCL8, CXCL10, and CXCL13 are significantly elevated in the saliva of patients with Sjögren’s syndrome compared to healthy controls, and that their levels are correlated with the activity and severity of disease." (PMID 38714918, 2024).
vasculitis (13 papers, 2015 to 2024). "In Bechet’s disease, another vasculitis involving large vessels in vast majority of them, γδ T cells are shown to secrete TNF-α and CXCL8 causing activation signal and recruitment of neutrophils and monocytes to sites of infection and inflammation." (PMID 35813204, 2022).
autism spectrum disorder (12 papers, 2012 to 2025). A spectrum of developmental disorders that includes autism, and Asperger syndrome. "Samples from the brain and cerebrospinal fluid of patients with autism spectrum disorders show increased contents of inflammatory molecules, such as IL-1β, IL-6, TNF-α, MCP-1, and CXCL8/IL-8." (PMID 33506033, 2021).
diffuse large B-cell lymphoma (12 papers, 2016 to 2025). "NETs induced by tumor-derived CXCL8 coupled with CXCR2 promoted diffuse large B-cell lymphoma (DLBCL) progression by activating Toll-like receptor 9 (TLR9), an important DNA sensor, and its downstream pathways." (PMID 37198402, 2023). "Additionally, TANs in the TME of diffuse large B-cell lymphoma (DLBCL) can also increase the secretion of april mediated by CXCL8, and promote DLBCL progression." (PMID 35372515, 2022).
HCMV infection (12 papers, 2007 to 2025). "Increased CXCL8 levels are observed during congenital human cytomegalovirus infection of brain vascular pericytes, which often leads to CNS abnormalities." (PMID 23029125, 2012).
palmoplantar pustulosis (12 papers, 2009 to 2024). A rare skin disease characterized by chronic eruption of sterile pustules on an erythematous and desquamative background, affecting the palms and soles, sometimes also the lateral aspects of hands and feet. "For example, the administration of monoclonal antibodies targeting α-chemokine interleukin-8 (also known as CXCL8 or IL-8) has demonstrated a significant reduction in clinical disease activity in cases of palmoplantar pustulosis." (PMID 38715098, 2024). "Another anti-CXCL8 antibody, HuMab 10F8, has been shown to reduce disease activity of palmoplantar pustulosis, a chronic inflammatory skin disease." (PMID 24276377, 2013).
plaque psoriasis (12 papers, 2013 to 2024). "In this observational study using transdermal analysis patch (TAP), levels of skin surface IL-1α, hBD-1, hBD-2, CXCL-1/2, and CXCL-8 of psoriasis vulgaris (PV) patients over biological therapy were assessed." (PMID 38003437, 2023). "Higher expression of neutrophil chemokines, including CXCL1, CXCL2, and CXCL8, were observed in GPP patients compared with plaque psoriasis patients." (PMID 38378928, 2024). "In addition, the IL-17A antagonist (secukinumab) used to treat moderate to severe plaque psoriasis can significantly inhibit the secretion of CXCL1 and CXCL8 by keratinocytes, and almost completely eliminate the infiltration of neutrophils in skin lesions." (PMID 33613635, 2021).
thyroid tumor (12 papers, 2014 to 2025). A benign or malignant neoplasm affecting the thyroid gland. "Currently, available evidence indicates that TPC-1 (RET/PTC1 mutated) and BCPAP (BRAF-V600E mutated) thyroid tumor cells secrete significantly different amounts of CXCL8 as measured in the cell culture supernatants, both basally and after TNF-α stimulation." (PMID 29977225, 2018). "The cytokines IL-6 and IL-8 (CXCL-8) are further key elements which are able to enhance 3D growth in PC-3 and have both already shown to induce 3D growth in thyroid tumor cells grown under 1g-conditions using the liquid overlay technique." (PMID 35252204, 2022). "The authors also demonstrated that MCs induced epithelial-to-mesenchymal transition (EMT) of thyroid tumor cell lines mainly through CXCL8 that activates the AKT-SLUG pathway." (PMID 33986723, 2020). "At difference with metformin, AICAR (another AMPK activator with known anticancer properties) was recently demonstrated to inhibit CXCL8 secretion and cell migration in the thyroid tumor cell lines TPC-1 and BCPAP and in normal human thyroid cells." (PMID 29977225, 2018). "Among them, CXCL8, previously demonstrated to exert several tumor-promoting effects in many human cancers, represents the most deeply investigated chemokine in thyroid tumor microenvironment." (PMID 29977225, 2018). "Targeting of CXCL8 in thyroid tumors provides therapeutic benefits in experimental models." (PMID 29977225, 2018). "Several attempts were done to reduce the secretion of CXCL8 in the thyroid tumor microenvironment." (PMID 29977225, 2018). "Inhibiting CXCL8 secretion turned out to be more difficult than it could be envisaged, even if several compounds allowed a certain degree of inhibition of CXCL8 secretion by thyroid tumor cells." (PMID 29977225, 2018). "CXCL8 and CCL2 are two chemokines secreted by thyroid tumor cells." (PMID 35498406, 2022).
acute lymphoblastic leukemia (11 papers, 2012 to 2025). Leukemia with an acute onset, characterized by the presence of lymphoblasts in the bone marrow and the peripheral blood. "MYC, CXCL8, and ATF3 were considered the hub genes and queried on Oncomine database and cBio portal platform to investigate their gene expression and genetic alterations in lymphoblastic leukemia." (PMID 32096603, 2020).
acute pyelonephritis (11 papers, 2009 to 2024). "In addition, gene polymorphisms of CXCL8/IL-8 seem to increase the susceptibility for acute pyelonephritis." (PMID 24066006, 2013). "CXCL8/IL-8 is a chemokine responsible for neutrophil infiltration into the urinary tract with an important role in acute pyelonephritis." (PMID 24692841, 2014). "On the other hand, the same research group previously found that there is a significant elevation of serum and urinary levels of IL-6 and CXCL8/IL-8 in children with acute pyelonephritis when compared to children with lower urinary tract infection." (PMID 24066006, 2013).
alcoholic liver diseases (11 papers, 2011 to 2024). A disorder caused by damage to the liver parenchyma due to alcohol consumption. "Different CXC chemokines, particularly CXCL8, mediates recruitment of neutrophils, which contribute to liver tissue damage in the alcoholic liver disease." (PMID 36077080, 2022).
Candida infection (11 papers, 2009 to 2025). "Probably, the higher level of TNF-α and CXCL8 detected in the saliva from elderly D.S. helps to avoid a more invasive C. albicans infection since these cytokines/chemokines play an important role in the innate resistance to oral and systemic Candida infections." (PMID 19327169, 2009).
cutaneous melanoma (11 papers, 2012 to 2026). A primary melanoma arising from atypical melanocytes in the skin. "If we can clarify the role of CXCL8 and JAK-STAT signaling pathways in EMT and apoptosis, it will have important implications for the diagnosis, treatment and screening of cutaneous melanoma." (PMID 37215082, 2023). "CXCL8 and JAK-STAT signaling pathways play a pivotal role in EMT and apoptosis in cutaneous melanoma." (PMID 37215082, 2023). "There may be a higher expression of CXCL8 and activation of the JAK-STAT signaling pathway present in cutaneous melanoma, in addition to the presence of epithelial-mesenchymal transition (EMT)." (PMID 37215082, 2023).
dental caries (11 papers, 2013 to 2025). The decay of a tooth, in which it becomes softened, discolored, and/or porous. "By producing and secreting TNF-α, IL-1, and CXCL8, immature dendritic cells (DC) contribute to the immune response of human dental pulp to oral pathogens entering dentin during dental caries." (PMID 37179325, 2023). "There are seven key proteins involved in the action of curcumin on dental caries: MAPK1, BCL2, KRAS, CXCL8, TGFB1, MMP9, and IL1B, all of which spontaneously bind curcumin." (PMID 38920854, 2024). "A distinct bacterial community structure and a differential expression of innate immune responses were observed in dental caries of Mexican individuals, with 2 genera, Olsenella and Parascardovia, exclusively found in moderate caries, and IL1β, IL6 and CXCL8 being overexpressed in dental caries." (PMID 36569197, 2022).
hematoma (11 papers, 2014 to 2025). A hematoma is a collection of blood from a vascular structure into an extravascular space. "Nevertheless, in the retrospective cohort of Pripp and Stanisic that included 93 patients, an association between increased hematoma fluid CXCL8 (IL-8) and reduced risk of recurrence in need of reoperation was indicated." (PMID 37510193, 2023). "Another study has found that patients with high concentrations of anti-inflammatory cytokine IL-10 also had high values for IL-6 and CXCL8, in addition to a tendency to be associated with a separated or layer type of hematoma." (PMID 29107999, 2017). "Consequently, the inverse relationship between CXCL8 and RrR could be due to its association with types of hematoma densities with a lower risk of RrR in this cohort." (PMID 29107999, 2017). "In both the blood and hematoma fluid samples, CXCL8 did not have significant loading values above 0.4." (PMID 24587250, 2014). "The IL-6 and CXCL8 in blood samples and CCL2, IL-5 and IL-13 in hematoma samples did not have significant standardized loadings, and were therefore excluded from the statistical models." (PMID 24587250, 2014).
hepatitis B (11 papers, 2011 to 2025). "We identified quercetin acted on the targets (AKT1, FOS, CCL2, and CXCL8) through key signal pathways (toll-like receptor signal pathway, hepatitis B, cell senescence, and chemokine signaling pathway) to exert treatment effects on CHB by use of a network pharmacological method." (PMID 33623529, 2021). "In this study, AKT1 and CXCL8 are enriched in hepatitis B (hsa05161), which may be involved in the regulation of HBV replication." (PMID 33623529, 2021). "Topological analysis indicated that AKT1, FOS, CCL2, CXCL8, and CXCL10 are hub genes; TLR signaling pathway, cellular senescence, hepatitis B, and chemokine signaling pathway are key pathways in the IGP network." (PMID 33623529, 2021).
irritable bowel syndrome (11 papers, 2016 to 2025). Irritable bowel syndrome (IBS) is a chronic functional condition of the lower gastrointestinal (GI) tract characterized by abdominal pain or discomfort and disordered bowel habit (diarrhea, constipation, or fluctuation between the two). "A similar pattern was seen for the Rome III constipation/defecation subscore, Rome III irritable bowel syndrome (IBS) criteria, and NMSS score and plasma CXCL8." (PMID 33557896, 2021).
obstructive sleep apnea (11 papers, 2016 to 2025). "Elevated CXCL8 levels have been associated with obstructive sleep apnea syndrome in children and adults." (PMID 40198463, 2025).
pemphigus (11 papers, 2017 to 2025). Pemphigus is a group of rare autoimmune diseases that cause blistering of the skin and mucous membranes (mouth, nose, throat, eyes, and genitals).This conditioncan occur at any age, but often strikes people in middle or older age. "CXCL8 has previously been reported by us and others to be elevated in pemphigus versus healthy control skin." (PMID 39911479, 2024). "We also found the potential for CXCL8 to be a used for a targeted treatment plan given its unique expression in pemphigus patients in our meta-analysis." (PMID 39911479, 2024). "CXCL8 and CXCL10 mediate recruitment of leukocytes to the skin from the blood, and have been implicated in the pathogenesis of human pemphigus." (PMID 34660634, 2021). "Specifically, we noted a unique expression of IFNG in DLE (p = 0.0213), a unique expression of TRAT1 and FOXO3A in EL patients (p < 0.0001 and p < 0.0001), and CXCL8 and CSF3R in pemphigus patients (p = 0.0002 and p = 0.0016)." (PMID 39911479, 2024). "Among the uniquely expressed genes in each disease, we observed significantly expressed IFNG in Discoid Lupus Erythematosus, TRAT1 in Epitheliotropic Lymphoma, and CXCL8 and CSF3R in pemphigus affected dogs." (PMID 39911479, 2024). "We validated significant upregulation of IFNG in DLE (p ~ 0.01), and a significant upregulation of CXCL8 and CSF3R in pemphigus." (PMID 39911479, 2024).
pulmonary hypertension (11 papers, 2007 to 2025). Increased pressure within the pulmonary circulation due to lung or heart disorder. "CXCL8 (IL-8) and its receptors CXCR1 and CXCR2 are upregulated in pulmonary arterial hypertension, with CXCL8 promoting the recruitment and activation of inflammatory cells through binding to CXCR1/2, exacerbating pulmonary artery inflammation and remodeling." (PMID 40385572, 2025).
thyroid (11 papers, 2011 to 2026). "In addition, Visciano and his colleagues used in vitro cell culture to demonstrate that (IL-8) CXCL8 induces EMT in TC and enhances the stemness of thyroid CSCs through the Akt-Slug signaling pathway." (PMID 35479325, 2022). "A study conducted in a large series of PTCs with and without associated thyroiditis showed that CCL20 and CXCL8 were significantly higher in PTC samples compared to normal thyroid, regardless of the tumor genetic background and the presence or absence of thyroiditis." (PMID 33986723, 2020).
vitamin D deficiency (11 papers, 2014 to 2025). A nutritional condition produced by a deficiency of VITAMIN D in the diet, insufficient production of vitamin D in the skin, inadequate absorption of vitamin D from the diet, or abnormal conversion of vitamin D to its bioactive metabolites. "Vitamin D deficiency was linked to the reduction of such chemokines as MIP-1α (CCL3) and IL-8 (CXCL8)." (PMID 34698104, 2021).